OAS1 (2'-5'-oligoadenylate synthetase 1)
Diseases named in the same sentence as OAS1 in open-access papers (continued):
Sharing a sentence is not in itself a finding about the gene and the disease.
COVID-19 (continued). "Nevertheless, we identified cases (for example, DR1, OAS1-3, TOMM7, MUC20) in which selection or archaic introgression contributed to changes in both SARS-CoV-2 immune responses and COVID-19 outcome." (PMID 37558883, 2023). "Results demonstrated that OAS1, OAS2, OAS3, and OASL were all highly expressed in SARS-CoV-2 infected NHBE (OAS 1 − 3, P < 0.01) and in the blood leucocytes of COVID-19 patients (all P < 0.001)." (PMID 36949448, 2023). "In the COVID-19 group, the TYK2 rs2304256, OAS1 rs10774671, CD40 rs4813003 and FCGR2A rs1801274 homozygote and heterozygote frequencies were in accordance with those indicated by the Hardy–Weinberg principle (p > 0.05)." (PMID 37896870, 2023). "While a protective effect of OAS1, IRF9, and IFI6 in asymptomatic and mild COVID-19 is confirmed, the role of TGFB1 and CCL5 is still controversial." (PMID 37389217, 2023). "The following four genes were enriched in the related pathways of coronavirus disease (COVID-19) from KEGG database: FCGR2A (FcRII–A), IRF9, OAS1(2′-5′-oligoadenylate synthetase 1) and CYBB (NOX2)." (PMID 36555339, 2022). "The MR analyses using these sQTLs as instruments suggested that alternative splicing events of the OAS1 and ICAM1 in some tissues (including adipose, adrenal gland and artery tissues) showed marginal effects on COVID-19 severity (MR P value<1 × 10−3)." (PMID 35772218, 2022). "We identified accessible proxy SNPs in LD with the COVID-19 sentinel rs10774671 in the promoter of OAS3, and accessible proxies interacting with OAS1 and OAS2 in all immune cell types analyzed." (PMID 35659055, 2022). "Four genes: FCGR2A (FcRII–A), IRF9, OAS1 (2′–5′-oligoadenylate synthetase 1) and CYBB (also known as NOX2) were highlighted in the related pathways of coronavirus disease (COVID-19) from KEGG database." (PMID 36555339, 2022). "IFNAR2 was significantly upregulated in severe COVID-19 patients (FDR = 0.0075), and both OAS1 and OAS3 were upregulated in T cells from severe COVID-19 patients compared to those with mild disease." (PMID 35659055, 2022). "Five hub genes shared by RA, COVID-19, and SAB were IFI44, OAS1, IFI44L, ISG15, and HERC5, and they were found to be closely associated with the immune system response to viral infection and bacterial infection using Metascape analysis." (PMID 36189314, 2022). "Genes involved in antiviral activity (i.e., ISG15, MX1, OAS1) and hyper-responsiveness of the immune system (i.e., TNFAIP8L2) were over-expressed in neutrophils from deceased COVID-19 patients." (PMID 34012444, 2021). "Thus, genetic variants that reduce OAS1 expression are likely to impair the degradation of SARS-CoV-2 RNA and antiviral responses triggered by NCM, which may contribute to the pathogenesis of severe COVID-19 illness." (PMID 34799557, 2021). "This study highlights the importance of endomembrane targeting for the antiviral specificity of OAS1 and suggests that early control of SARS-CoV-2 replication through OAS1 p46 is an important determinant of COVID-19 severity." (PMID 34342578, 2021). "Several other loci show no previously documented genome-wide significant associations, despite the high significance and attractive candidate genes for COVID-19 (for example, CXCR6, LZTFL1, IFNAR2 and OAS1/OAS2/OAS3 loci)." (PMID 34237774, 2021). "OAS1, OAS2, OAS3, IFIT1, IFIT3, IFI44, IFI44L and IFITM1: Current COVID-19 genetic studies incline to analyze those genes together." (PMID 34109284, 2021). "Seven of our significant genes higher (GALNT14, OAS1, CCRL2, OAS3, CCR1, OAS2, SIPA1L2) in COVID-19 and two lower (HLA-DPB1, HLA-DQA2) were identified to overlap." (PMID 34335605, 2021). "Comparison of severe and mild Symptomatic COVID-19 cases revealed an upregulation of CD177, the neutrophil marker, CXCL16, MAPKMAPK2 and IRF2BP2 with downregulation of ISGs; IFIT, IFIT3, OAS1, OAS2, LY6E and MX1 in severe cases." (PMID 34824360, 2021).
COVID-19 (continued). "This ‘coloc-first’ approach identified four proteins (ABO, FAS, OAS1, THBS3) with evidence of genetic colocalisation (PP.H4 >0.8) with four out of seven COVID-19 phenotypes." (PMID 34402426, 2021). "Although these participants were recruited at different times after recovery, we were able to show a consistent result for MTB-stimulated IFN-γ SPUs as well as gene expression levels of OAS1, MAVS and SOCS3 between COVID-19 sub-groups in comparison with controls." (PMID 41468475, 2025). "The higher levels of OAS1 and MAVS observed in COVID-19 indicates activation induced by SARS-CoV-2 whilst the absence of differences between IFN-1α levels may be due to downregulation of T cell activation in this group." (PMID 41468475, 2025). "Our research indicated that certain polymorphisms in the genes ACE2 rs2074192, IFNAR2 rs2236757, OAS1 rs10774671, OAS3 rs10735079, CD40 rs4813003, FCGR2A rs1801274 and CASP3 rs113420705 could predict cytokine responses in pediatric COVID-19 patients." (PMID 40066463, 2025). "COVID-19 cases displayed higher expression of mRNA levels of MAVS, OAS-1, and SOCS3 (p < 0.05)." (PMID 41468475, 2025). "The hypermethylated genes with the lowest p values for hospitalized COVID-19 patients at inclusion (T1) vs. at 6 weeks post-inclusion (T2) were PARP9, ABCA1, MX1, OAS1, ARID5B, and the hypomethylated genes included TMEM131, ROCK1, IFNGR1, CFAP61, VRK2, and C6orf138." (PMID 41227320, 2025). "We observe an upregulation of genes involved in antiviral response pathways, including OAS1 that mediates RNase L pathway, IFIT1, and APOE at the upper respiratory airway of COVID-19-infected Ghanaians compared with a relevant publicly available dataset (GSE166530) from an Indian COVID-19 cohort." (PMID 38375062, 2024). "Notably, genes such as IFI27 and OAS1, which are involved in defense responses and apoptotic signaling, were upregulated in both PBMC and lung samples of COVID-19 patients." (PMID 38681774, 2023). "In addition to the OAS1 eQTL, OAS3 eQTL in fibroblasts was also colocalized with the COVID-19 GWAS locus (posterior probability = 0.99)." (PMID 37308670, 2023). "Then, regression analyses indicated that 9 prognostic genes (including ANPEP, OAS1, SCGB1A1, HLA‐A, NPPB, FGB, CCL2, TLR4, and SERPINE1) might play important roles in quercetin for treating UCEC/COVID-19." (PMID 36969077, 2023). "The Cox regression analyses suggested that 9 prognostic genes (ANPEP, OAS1, SCGB1A1, HLA‐A, NPPB, FGB, CCL2, TLR4, and SERPINE1) might act critical roles in the treatment of UCEC/COVID-19." (PMID 36969077, 2023). "In this study, the relative expression of IRF9, CCL5, IFI6, TGFB1, IL1B, OAS1, and TFRC genes (related to immunity and antiviral activity) was analyzed in upper airway samples from 127 individuals (97 COVID-19 positive and 30 controls) by using a two-step RT-PCR." (PMID 37389217, 2023). "We identify that alternative splicing in lung, rather than total expression of OAS1, ATP11A, DPP9 and NPNT, is associated with COVID-19 severity." (PMID 37794074, 2023). "OAS1 and SERPINA1 were targets of existing drugs in trials as potential COVID-19 treatments." (PMID 35772218, 2022). "We functionally annotated several additional variants within OAS1 and OAS3 that were significantly associated with COVID-19 hospitalization in patients of European ancestry but did not yet reach significance in patients of African ancestry." (PMID 35835913, 2022). "Furthermore, results evidenced that COVID-19-positive patients with higher expressions of JAK2 and STAT1 showed increased MX1, MX2, ISG15, and OAS1 mRNA levels." (PMID 36298734, 2022). "IFI44, OAS1, IFI44L, ISG15, and HERC5 are the five hub genes shared by RA, COVID-19, and SAB." (PMID 36189314, 2022). "A two-sample Mendelian randomization study of 931 proteins showed that increased OAS1 levels in the non-infectious state strongly correlated with reduced risks for SARS-CoV-2 susceptibility and COVID-19 severity." (PMID 36211429, 2022).
COVID-19 (continued). "Expression of MX1, MX2, ISG15, and OAS1 (four well-known IFN-stimulated genes (ISGs)) displayed upregulation in COVID-19-positive vs. -negative patients." (PMID 36298734, 2022). "Collectively, these findings suggested that OAS1 may serve as a protective factor against SARS-CoV-2 infection and poor COVID-19 outcomes in the wide organs and tissues." (PMID 35082790, 2021). "To better understand the antiviral defenses relevant to COVID-19, we used interferon-stimulated gene (ISG) expression screening to reveal that 2′-5′-oligoadenylate synthetase 1 (OAS1), through ribonuclease L, potently inhibits severe acute respiratory syndrome coronavirus 2 (SARS-CoV-2)." (PMID 34581622, 2021). "Hospitalized COVID-19 patients lacking the p46 transcript had worse clinical outcomes than those who expressed prenylated OAS1." (PMID 34581622, 2021). "This difference was entirely driven by the overrepresentation of patients in the severe COVID-19 group who did not express any prenylated OAS1." (PMID 34581622, 2021). "However, we found higher levels of OAS-1, MAVS and SOCS3 in COVID-19 cases as compared to HC group." (PMID 41468475, 2025). "Genetic variations within IFNAR2, OAS1, and OAS3 could potentially disrupt this signaling pathway, leading to decreased protein abundance, impaired receptor internalization, or altered ligand interactions, thereby exacerbating the severity of COVID-19." (PMID 40278335, 2025). "Thus, the aim of this study was to investigate the potential association between genic variants at rs1024611 (A>G), rs10774671 (A>G), and rs10406145 (G>C) of CCL2, OAS1, and DPP9 genes, respectively, and the severity of COVID-19 in a population from Quito, Ecuador." (PMID 38694517, 2024). "Furthermore, we did not observe statistically significant differences in COVID-19 severity between patients with either OAS1 rs10774671 or OAS3 rs10735079." (PMID 39296547, 2024). "Notably, in the present work, we demonstrated that the expressions of the ISGs MX1, MX2, ISG15, and OAS1 were upregulated in COVID-19-positive vs. -negative patients." (PMID 36298734, 2022). "However, billions of humans do not have the prenylated OAS1 haplotype, including many experiencing severe COVID-19." (PMID 34581622, 2021). "p46 mRNA levels were almost identical in individuals who expressed prenylated OAS1 regardless of whether they experienced mild or severe COVID-19." (PMID 34581622, 2021). "Finally, in individuals with moderate SARS-CoV-2 infection, 2’-5’-Oligoadenylate Synthetase 1 (OAS1), OAS2, OAS3, and T cell Immunoreceptor with Ig and ITIM domains (TIGIT) were elevated, but these levels significantly decreased with increased COVID-19 severity." (PMID 39928675, 2025).
viral infection (127 papers, 2007 to 2026). "In this report, they observed an upregulation of HSPAIL, a gene involved in host epigenetic regulation that leads to increased SARS-CoV-2 replication and the OAS1 gene associated with viral infection susceptibility." (PMID 38013836, 2023). "OAS1 functions as a sensor of viral infections, recognizing dsRNA, a pathogen-associated molecular pattern (PAMP), and subsequently activating the innate immune system to exert antiviral activity." (PMID 37928544, 2023). "Accordingly, virus infection causes higher expression of IFNa2, IFNb1, OAS1, and STAT2 in Nlrx1−/− mice when compared to wild-type mice." (PMID 33525590, 2021). "Among the OAS family members, Oas1 had also been linked to onset of T1D in the context of viral infections." (PMID 32625203, 2020). "As a functional OAS1 polymorphic marker, rs10774671 was reported to be associated with disease/viral infection." (PMID 30497421, 2018). "A SNP in the acceptor site of an antiviral enzyme OAS1 associates with the level of OAS1 activity and susceptibility to viral infections." (PMID 30245696, 2018). "For example, SNPs in OAS1 have been identified as candidates for susceptibility to viral infections, such as West Nile virus, hepatitis C, Chikungunya, dengue and measles." (PMID 30497421, 2018). "OAS1 belongs to the OAS family of proteins known to be active synthetases that synthesize 2′-5′-linked oligoadenylates in response to viral infections, thereby affecting an early step of the viral replication cycle." (PMID 30581844, 2018). "The SS risk allele of rs10774671 has been shown by others to be associated with reduced OAS1 enzymatic activity and ability to clear viral infections, as well as reduced responsiveness to IFN treatment." (PMID 28640813, 2017). "Notably, the OAS1 (2′-5′-oligoadenylate synthetase 1) gene, a key component of the innate immune response against viral infections, has recently been implicated in various cancers." (PMID 41584451, 2025). "In accordance with this function, human OAS1 mainly affects susceptibility to viral infections." (PMID 30497421, 2018). "Mutations in either the OAS1 or RNASEL genes may also modulate the outcome of WNV-induced disease or other viral infections in horses." (PMID 17822564, 2007). "Although OAS1 expression is initiated by inflammation, the OAS1 protein is activated by the presence of dsRNA, attributed to viral infection." (PMID 39859237, 2025). "OAS1 plays a significant role in the immune response to viral infections, particularly evident from its involvement in multiple GO terms related to immune processes." (PMID 39282474, 2024). "We thus investigated the expression of four ISGs acting on different steps of viral infection (i.e., OAS1, IFITM3, ISG15, MxA) in lysates of HAEs infected with A/H3N2, A/H1N1, D614G and Omicron viruses in single and coinfections." (PMID 39038029, 2024). "These interactions suggest that OAS1 not only responds to viral infections but also influences broader immune regulatory networks that control inflammation and cellular signaling in response to pathogens." (PMID 39282474, 2024). "OAS1 and HSPAIL are genes associated with increased receptiveness to viral infections while CCR2 and TYK2 are also important drivers of inflammation." (PMID 38013836, 2023). "OAS1 enhances the immune cell’s capacity to fight viral infections by triggering the interferon signaling pathway." (PMID 38103068, 2023). "Recent evolutionary studies about the human immune response against viral infections point out that OAS1 plays an important role in SARS-CoV-2 pathogenesis." (PMID 36298734, 2022). "Subsequently, we visualized how those terms were linked to one another, which showed that for the horse there was a strong connection between liver pathology and viral infection, most likely driven by the activation of ISGs such as OAS1, MX1, and ISG20." (PMID 35527255, 2022).
viral infection (continued). "As the coding gene of 2’-5’-oligoadenylates (2-5As), OAS1 was proved to be essential for distinctive biological processes, including anti-virus infection, cell growth, as well as cell apoptosis in tumors." (PMID 36341378, 2022). "OAS1 restricts viral infection by degrading viral RNA in combination with RNase L, resulting in an inhibition of viral replication; and polymorphisms of OAS1 have been shown to associate with dengue patients requiring hospitalisation." (PMID 35869167, 2022). "IL-27 has been shown to play an important role in stimulating the transcription of cytosolic innate immune sensors, such as Mx1, Oas1, and Oas2, during viral infection." (PMID 36678402, 2022). "We validated the relevance of MX1, MX2, ISG15, and OAS1 in the context of viral infections in cell cultures in vitro and in a pre-clinical model of Coronavirus infection." (PMID 36298734, 2022). "Again, IFNB1 and OAS1 mRNA levels were lower in the mutant compared to the revertant virus infection at several time points." (PMID 32365141, 2020). "The MERS-CoV-shared genes KRT6B and TNFAIP3 had a high p-value associated with SARS-CoV-2, whereas genes such as OAS1-3, IRF9, IRF7, STAT1, PML and IFIH1 were highly associated with host responses to viral infections and type I interferon." (PMID 33301474, 2020). "The interferon-induced OAS system is well described, at least regarding the molecular mechanisms involved, and the importance of the OAS1 proteins in the innate immune system and the protection against viral infections is evident." (PMID 31817188, 2019). "2'‐5'‐oligoadenylate synthetase 2 (OAS2) gene, together with neighboring OAS1 and OAS3 gene, encodes enzymes participating in innate immunity response to viral infection." (PMID 30859738, 2019). "This pathway should indeed lead to an overall anti-viral resistance, but the OAS1 p46 interestingly confers better protection against some forms of viral infection, which will be discussed shortly." (PMID 31817188, 2019). "OAS1 is an IFN-induced antiviral enzyme that can defend against the viral infections by recognizing viral dsRNA." (PMID 31024609, 2019). "Previously it was thought that OAS1, 2, and 3 were involved in activating RNase L during viral infection, until recently Li and colleagues observed that OAS3 is mainly responsible for producing the 2–5A RNase L activators." (PMID 28580319, 2017). "The SNP rs10774671 at intron 5 of the OAS1 gene affects pre-mRNA splicing and the enzymatic activities of various isoforms of OAS1, which have been intensively studied in the context of viral infections, including HCV." (PMID 29242559, 2017). "OAS1 is a well-known molecule that restricts viral infection by degrading viral RNA in combination with RNase L, resulting in the inhibition of viral replication." (PMID 29242559, 2017). "OAS1 is a member of the 2'-5'-oligoadenylate synthetase family, which is upregulated by type I IFNs during innate immune responses to viral infection and activates latent RNase L, leading to viral RNA degradation and clearance." (PMID 28640813, 2017). "Among these, the expression of Mx1, Mx2, TRIM22, WARS, ISG15, ISG20, UBA7, DDX58, and OAS1-3 were up-regulated, representing an increased innate immune response against viral infections." (PMID 25883591, 2015). "OAS1 (2’-5’-oligoadenylate synthase 1) activates latent RNase L following viral infections and results in degradation of viral RNA." (PMID 25874939, 2015). "Previous studies have also shown that OAS1 is up-regulated more readily than other ISGs following viral infection in swine cells." (PMID 23875024, 2013). "Analysis of host genes germane to viral infections disclosed that antiviral genes such as mx1 and oas1 were induced in the HIV brains while MHC Class I genes (hla-c, -b and -a) were relatively suppressed in the same group." (PMID 23355888, 2013). "OAS1 and OAS2 encode for two enzymes of the 2–5A synthetase family, involved in the innate immune response to viral infections." (PMID 23272139, 2012).